TCF7L2 (transcription factor 7 like 2)
Diseases named in the same sentence as TCF7L2 in open-access papers (continued):
Sharing a sentence is not in itself a finding about the gene and the disease.
mental disorder (14 papers, 2011 to 2025). A disease that has its basis in the disruption of mental process. "For example, crossing B6 males with deletion of Cacna1c and Tcf7l2 genes associated with multiple psychiatric diseases with wild-type females from 30 inbred laboratory strains resulted in highly variable, sometimes opposing, effects." (PMID 35813596, 2022). "Considering that Tcf7l2 is associated with mental disorders, our findings also provide a new insight into the aetiology of thalamic and habenular dysfunction that are observed in these disorders." (PMID 32675279, 2020). "Among genes that encode downstream nuclear effectors of the canonical Wnt/β‐catenin pathway, only TCF7L2 has been repeatedly associated with mental disorders in both gene candidate and genome‐wide association studies." (PMID 31218672, 2019). "Evidence from animal studies strongly implicates canonical Wnt/β‐catenin signaling and TCF7L2‐dependent transcription in the development of these impairments, and human genetic studies have found associations between this pathway and major mental disorders." (PMID 31218672, 2019). "Ion channels and neurotransmitter genes, some of which were dysregulated in mice with postnatal Tcf7l2 knockout, are also often associated with psychiatric disorders." (PMID 31218672, 2019). "All of these genes have been linked with SCZ 119, 120, what shows that TCF7L2 might play a role in the etiology of mental disorders." (PMID 31218672, 2019). "These genetic data are a strong indication that TCF7L2 is involved in pathological processes that result in mental disorders." (PMID 31218672, 2019). "These multiple genetic overlaps between embryonic and adult TCF7L2‐target genes in the thalamus and psychiatric conditions imply TCF7L2‐mediated thalamic alterations in the pathogenesis of mental disorders." (PMID 31218672, 2019). "Further research is needed to elucidate the role of ZNF804A and TCF7L2 in thalamus development and in the etiology of psychiatric disorders." (PMID 25963709, 2016). "Altogether, genetic alterations in individuals with mental disorders and behavioral deficits in genetically modified animals have provided convincing evidence that the canonical Wnt/β‐catenin pathway and LEF1/TCFs (particularly TCF7L2) are involved in the pathogenesis of mental disorders." (PMID 31218672, 2019). "Among TCF family, particular attention is given to the role of TCF7L2, for having a central role in neural stem cell differentiation and postmitotic differentiation of some brain regions, impairments of which might contribute to mental disorders." (PMID 39868289, 2025). "Among the TCF family, particular attention is given to the role of TCF7L2, for having a central role in neural stem cell differentiation and postmitotic differentiation of some brain regions, impairments of which might contribute to mental disorders." (PMID 40534837, 2025). "Our study demonstrates that TCF7L2 carries pleiotropic effects and provides added evidence of possible common genetic underpinning that may explain the historical comorbidities between T2D and psychiatric disorders." (PMID 22046400, 2011). "WNT/β-catenin signaling, as reported by transcription factor 7-like 2 (TCF7L2)-dependent transcription, is involved in the onset of mental disorders and behavioral deficits." (PMID 39120307, 2024). "Particular attention is given to the role of TCF7L2, as it has been recently identified as having a central role in neural stem cell differentiation and postmitotic differentiation of some brain regions, impairments of which might contribute to mental disorders." (PMID 31218672, 2019). "It is noted that 7 genes, DAO, PRDX6, KCNN3, TCF7L2, RFX4, FYN, and B3GAT2 (yellow-colored nodes), relevant to psychiatric disorders are involved and interestingly these genes except B3GAT2 constitute a connected subgraph." (PMID 27510319, 2016). "Possible direct links between mental disorders, Wnt, TCF7L2, and oligodendrogenesis have not been investigated." (PMID 31218672, 2019).
hepatocellular carcinoma (13 papers, 2011 to 2024). A malignant tumor that arises from hepatocytes. "CNV-gene TCF7L2 played a key role in Wnt signaling and was associated with susceptibility of hepatocellular carcinoma." (PMID 24897108, 2014). "It is also a causative factor for the progression of hepatocellular carcinoma, which might be ascribed to polymorphisms in TCF7L2 rs290487 and rs6585194 gene along with the presence of SNPs rs290481, rs290487, and rs29048 at 3′ end of TCF7L2 gene." (PMID 34805412, 2021). "Because TCF4 (TCF7L2) is one of the major Wnt/β-catenin signaling-associated transcription factors and binds to Irs1 promotor in the rat hepatoma cell line H4IIE16, 21, the effect of dominant-negative TCF4 cDNA (DN-TCF4) on the regulation of Irs1 in primary hepatocytes was examined." (PMID 28710407, 2017). "For example, the lncRNA MALAT1, which owned the largest subnetwork and largest loss proportion, was found to regulate cancer glucose metabolism by enhancing mTOR-mediated translation of TCF7L2 in hepatocellular carcinoma." (PMID 34222227, 2021). "Consistent with the mRNA data above, Tcf7l2 silencing led to an increase in HNF4α protein levels 24 and 48 h after electroporation in hepatoma cells." (PMID 25414334, 2014). "We highlight that TCF7L2 has a diverse role in hepatoma cells and, through direct and indirect gene regulation, regulates multiple pathways." (PMID 25414334, 2014). "An important observation from our analysis is that wild-type TCF7L2 appears to primarily act to induce gene expression in hepatoma cells." (PMID 25414334, 2014). "To examine this more closely, we performed co-silencing experiments of TCF7L2 and HNF4α, and examined the expression of several metabolic genes in the hepatoma cells." (PMID 25414334, 2014). "To begin to understand the mechanisms of target gene regulation by Tcf7l2, we first employed a time-course RNA-Seq approach following transient Tcf7l2 silencing in hepatoma cells." (PMID 25414334, 2014). "Given the known roles of these genes in hepatic lipid metabolism, it is highly likely that reduced Tcf7l2 expression promotes an increase in cholesterol synthesis, trafficking and secretion from hepatoma cells." (PMID 25414334, 2014). "It is apparent from our study that TCF7L2 has an important and diverse molecular role in hepatoma cells, and that it regulates an array of pathways essential for hepatocyte physiology." (PMID 25414334, 2014). "For the first time, we demonstrate that the balance between TCF7L2 and HNF4α levels determines the expression of numerous metabolic genes in hepatoma cells." (PMID 25414334, 2014). "We employed a temporal RNA-Seq approach to examine gene expression 3–96 h following Tcf7l2 silencing in rat hepatoma cells, and combined this with ChIP-Seq to investigate mechanisms of target gene regulation by TCF7L2." (PMID 25414334, 2014). "Using a combination of temporal RNA-Seq and ChIP-Seq tools in wild-type and TCF7L2-silenced hepatoma cells, we first focused on identifying genes that were directly regulated by TCF7L2 DNA binding." (PMID 25414334, 2014). "In the current study, we employed an integrative genomics study to examine the mechanisms of TCF7L2-target gene regulation in hepatoma cells." (PMID 25414334, 2014). "We also describe the transcriptional partners of TCF7L2 and, in particular, identify the master-regulator hepatocyte nuclear factor 4-alpha (HNF4α), as a key transcriptional partner of TCF7L2 in the hepatoma cells, particularly in the regulation of metabolic genes." (PMID 25414334, 2014). "Genes regulating glycogen metabolism (Gys2), glycolysis (Aldob and Eno2) and glucose transport (Slc2a2) were all affected by Tcf7l2 silencing in the hepatoma cells, suggesting that TCF7L2 activity is an important determinant of carbohydrate metabolism overall in the liver." (PMID 25414334, 2014).
hepatocellular carcinoma (continued). "The data in current study highlight several important and new concepts related to TCF7L2 activity in hepatoma cells that may be of significance to hepatocyte development and physiology in animals and humans." (PMID 25414334, 2014). "In general Tcf7l2 silencing was associated with a gene expression program consistent with reduced cell invasiveness, diminished capacity for liver injury repair and a mesenchymal to epithelial transition (MET) in hepatoma cells." (PMID 25414334, 2014). "In addition to these pathways, our data also demonstrate that TCF7L2 is a major regulator of metabolic genes in hepatoma cells." (PMID 25414334, 2014). "Indeed, TCF7L2 acts as a tumor suppressor in colon cell proliferation and tumorigenesis, while some isoforms contribute to hepatocellular carcinoma malignant phenotypes." (PMID 22087314, 2011). "The Tet-on system induced rapid liver enlargement and tumorigenesis, which often progressed to hepatocellular carcinoma (HCC) with various oncogenes such as CTNNB1mt and tcf7l2, krasV12, HCP, xmrk, and mouse Myc." (PMID 37759472, 2023). "Together these data highlight that TCF7L2 DNA occupancy can directly regulate the expression of multiple cellular and metabolic genes in hepatoma cells, many of which have not previously been shown to be directly regulated by TCF7L2." (PMID 25414334, 2014). "The down-regulation of insulin signaling and PPARα transcription in this analysis reflects the increased expression of gluconeogenesis and lipid synthesis and trafficking genes in the hepatoma cells following Tcf7l2 silencing, as both a negative regulators of these pathways." (PMID 25414334, 2014). "Recent studies have shown that TIP5 exerts oncogenic effects in Hepatocellular Carcinoma (HCC) by activating β-catenin/TCF7L2 signaling, suggesting that TIP5 may be a promising therapeutic target for HCC." (PMID 37925811, 2024). "Finally to test whether HNF4α was required for the full effect of Tcf7l2 silencing on gene expression in the hepatoma cells, we analyzed the effect of Hnf4a silencing with and without concomitant Tcf7l2 silencing on a subset of our DEGs." (PMID 25414334, 2014).
lung carcinoma (12 papers, 2012 to 2025). "Recently, one study identified several mutations in the TCF7L2 HMG box that are associated with lung cancer." (PMID 35048372, 2022). "A study provided summary evidence that TCF7L2 genes are associated with the risk of breast, colorectal, and lung cancer and glioma." (PMID 34305772, 2021). "High expression or mutations of TCF7L2 were found in several human tumors such as colorectal cancer, breast cancer, liver carcinoma, or lung cancer." (PMID 26289446, 2015). "Among patients, frame shift insertion/deletion of ATR and the major mutation of RB1 (RB1 p.F739L) and TCF7L2 (TCF7L2 p.I271N) changed the protein structure during simulation, suggesting that they might play an important role in the development of lung cancer." (PMID 34970478, 2021). "However, the study of TCF7L2 mutation mainly focused on breast, colorectal, and lung cancer." (PMID 34305772, 2021). "Since the risk allele rs6983267 G has been shown to have a stronger affinity to TCF7L2 and may induce enhanced MYC expression, rs6983267 might be associated with survival in patients with lung cancer." (PMID 22848662, 2012). "As the downstream effector of Wingless‐related integration site signaling, transcription Factor 7 Like 2 (TCF7L2) is essential for regulating growth and metastasis in multiple cancers, such as lung cancer and CRC." (PMID 38785271, 2024).
coronary artery disease (10 papers, 2008 to 2025). "Yet, previous studies have found a positive association between the TCF7L2 rs790346 T- allele and development of coronary artery disease (CAD) in diabetic patients." (PMID 28220878, 2017). "For example, four SNPs (i.e., rs4506565, rs10885409, rs7901695, and rs4132670) in TCF7L2 have been reported to be associated with T2D, and SNP rs11196205 in TCF7L2 is associated with both T2D and coronary artery disease." (PMID 23626757, 2013). "In order to evaluate if TCF7L2 genotype was also associated with cardiovascular events in a population of individuals already with extensive coronary artery disease, we studied the patients from the MASS-II Trial." (PMID 19924244, 2009). "We genotyped the single nucleotide polymorphisms (SNP) rs7903146 of the TCF7L2 gene in 560 patients with known coronary disease enrolled in the MASS II (Medicine, Angioplasty, or Surgery Study) Trial and in 1,449 residents of Vitoria, in Southeast Brazil." (PMID 19055834, 2008). "Association between TCF7L2 variants and significant coronary artery disease in the total cohort." (PMID 21423583, 2011). "Association between TCF7L2 variants and the extent of coronary artery disease." (PMID 21423583, 2011). "Despite the fact that lipid metabolism may be a link between TCF7L2, adipocyte metabolism and coronary disease, few studies have evaluated fasting lipids, and the influence of gene variations on this gene and on postprandial lipids remains an unexplored field." (PMID 22916254, 2012). "This study aimed to evaluate the association between TCF7L2 polymorphism rs7903146 and coronary artery disease in diabetic and non-diabetic subjects." (PMID 19924244, 2009). "The study data showed a significant association between TCF7L2 rs7903146 genotypes and coronary artery disease in non-diabetic individuals, in both independent populations." (PMID 19924244, 2009). "In their report, they have not demonstrated a significant association between any TCF7L2 SNP with incident coronary disease, ischemic stroke, CVD, prevalent peripheral artery disease (PAD) or all-cause mortality in the full cohort nor when stratified by race or diabetic status." (PMID 19924244, 2009).
prediabetes (10 papers, 2012 to 2024). "Postprandial lipid responses to a standardized fat challenge test were performed in 620 Asian Indian subjects (310 with NGT and 310 with T2DM/prediabetes) and compared between the risk and wild genotypes of the rs7903146 TCF7L2 gene." (PMID 36263318, 2022). "The T allele (OR = 1.66, 95% CI 1.05–2.63, p = 0.03) and TT genotype of the TCF7L2 rs7903146 (OR = 3.27, 95% CI 1.63–6.55, P = 0.0005) were associated with prediabetes." (PMID 35292917, 2022). "Similarly, the risk of prediabetes was significantly elevated in carriers of the unfavorable T allele of the TCF7L2 gene (rs7903146)." (PMID 39767130, 2024). "The molecular mechanism of variation in TCF7L2 and risk of T2D and prediabetes is currently unknown." (PMID 35292917, 2022). "This cross-sectional study aimed to investigate the independent risk factors for prediabetes, considering the contribution of genetic factors (TCF7L2-rs7903146, IRS1-rs1801278, INSR-rs3745551, CDKN2A-rs10811661, and FTO-rs9939609), socio-economic status, and lifestyle factors." (PMID 26334876, 2015). "The genetic polymorphisms of TCF7L2 and PPARG, explored in our investigation, assume global relevance due to the increasing prevalence of prediabetes and T2D on a global scale." (PMID 39451528, 2024). "There was a significant increase in the risk of developing prediabetes for both the rs1801282 polymorphism of the PPARG gene and the rs7903146 polymorphism of the TCF7L2 gene." (PMID 39767130, 2024). "The expression of TCF7L2 gene in VAT was 11-fold higher in prediabetes group as compared to NGT (P<0.01) and 5.7-fold higher in T2DM group as compared to NGT group(P=0.003) and was significantly associated with PPTg and glucose levels." (PMID 36263318, 2022). "The expression of TCF7L2 gene in VAT was 11-fold higher in prediabetes group as compared to NGT (P<0.01) and 5.7-fold higher in T2DM group as compared to NGT group (P<0.01)." (PMID 36263318, 2022). "Several international studies have investigated the prevalence of PPARG (rs1801282) and TCF7L2 (rs7903146) genotypes in individuals with prediabetes belonging to different ethnicities with varying observations, but there is a lack of studies on the ethnic Kazakh population." (PMID 39767130, 2024). "Therefore, this study aims to investigate the genetic contribution of polymorphic variants of the TCF7L2 (rs7903146) and PPARG (rs1801282) genes to the risk of developing prediabetes in individuals of Kazakh ethnicity." (PMID 39767130, 2024). "The aim of this study was to assess the frequencies of two minor alleles of polymorphic variants in the TCF7L2 gene (rs7903146) and the PPARG gene (rs1801282), which are associated with the risk of prediabetes, in an ethnically homogeneous population of Kazakhs." (PMID 39451528, 2024). "The genetic contribution of the TCF7L2 rs7903146 polymorphism to the development of prediabetes has not been previously studied, which justifies the selection of this polymorphism for conducting replicative genotyping in cases of prediabetes within the Kazakh population." (PMID 39451528, 2024). "This case-control study aimed to investigate the distribution of TCF7L2 (rs7903146) and PPARG (rs1801282) genotypes in cases with prediabetes and healthy controls of Kazakh ethnicity." (PMID 39767130, 2024). "Despite these limitations, this study emphasizes the significant role of TCF7L2 (rs7903146) and PPARG (rs1801282) in prediabetes, suggesting their potential as biomarkers, particularly among individuals of Kazakh ethnicity." (PMID 39767130, 2024). "Numerous genes have been investigated concerning both T2DM and prediabetes, including PPARG (peroxisome proliferator-activated receptor gamma, rs1801282) and TCF7L2 (transcription factor 7-like 2, rs7903146)." (PMID 39767130, 2024).
prediabetes (continued). "In 30 subjects scheduled to undergo abdominal surgery (10 each with NGT, Prediabetes and T2DM), adipocyte TCF7L2 gene expression was also performed by real time qPCR and confirmed by protein expression in western blot." (PMID 36263318, 2022). "This has not been described before in prediabetes or T2D and may indicate that in parallel with the modification of the long-chain lysoPCs there is also a disturbed regulation of very-long-chain PCs in risk subjects carrying the TCF7L2 risk allele." (PMID 24205231, 2013). "Therefore, the study was designed to investigate both genetic (TCF7L2-rs7903146, IRS1-rs1801278, INSR-rs3745551, CDKN2A-rs10811661, and FTO-rs9939609) and environmental factors for prediabetes in a Vietnamese population." (PMID 26334876, 2015).
Stroke (10 papers, 2015 to 2025). Sudden impairment of blood flow to a part of the brain due to occlusion or rupture of an artery to the brain. "We previously found that subjects with the TT genotype of TCF7L2 rs7903146 variant, who consume a low-fat diet (LF) had a higher incidence of stroke than subjects with the CC genotype." (PMID 40050721, 2025). "Research has also demonstrated a protective role of the Mediterranean diet in gene/Mediterranean diet interactions for the risk TT allele of the TCF7L2-rs7903146 gene in stroke risk and mortality." (PMID 29686666, 2018). "Among them, we would like to underline that found with the TCF7L2-rs7903146 C>T SNP and the dietary intervention (MedDiet versus control) in determining stroke incidence." (PMID 27598147, 2016). "Studies have shown that some variants of TCF7L2 are associated with impaired lipid metabolism, especially a trend towards higher triglycerides, with an adverse effect on cardiovascular risk and stroke incidence." (PMID 26608632, 2015). "In the PREDIMED trial we showed that MedDiet intervention modulated the effects of the TCF7L2-rs7903146 C>T SNP on stroke incidence." (PMID 27598147, 2016).